ABHD4 (abhydrolase domain containing 4, N-acyl phospholipase B)
Synonyms: FLJ12816; ABH4
Tractability: PROTAC: ubiquitination databases record sites on it; its protein half-life has been measured.
Gene: Protein-coding gene on chromosome 14 (22,598,249 to 22,612,963, forward strand). Ensembl gene ENSG00000100439.
Pathways (Reactome):
Metabolism: Acyl chain remodelling of PE
Gene Ontology:
Molecular function: protein binding; hydrolase activity; phosphatidylcholine lysophospholipase activity
Biological process: N-acylphosphatidylethanolamine metabolic process; phosphatidic acid biosynthetic process; phosphatidylethanolamine acyl-chain remodeling; glycerophospholipid metabolic process
Cellular component: endoplasmic reticulum membrane; lipid droplet
Genetic constraint (gnomAD): Loss-of-function variants: 34 observed, 43.6 expected, observed/expected ratio (o/e) 0.78, 90% interval 0.59 to 1.04. The upper end of that interval is the gene's LOEUF score, 1.04, which puts it in group 4 of 6, group 1 being the genes least tolerant of losing a copy. Missense variants: 388 observed, 472.98 expected, observed/expected ratio (o/e) 0.82, 90% interval 0.75 to 0.89. Synonymous variants: 168 observed, 180.02 expected, observed/expected ratio (o/e) 0.93, 90% interval 0.82 to 1.06.
Homologues: Orthologues: chimpanzee ABHD4 (100% identical), macaque ABHD4 (99% identical), rabbit ABHD4 (97% identical), dog ABHD4 (96% identical), guinea pig ABHD4 (94% identical), pig ABHD4 (90% identical), mouse Abhd4 (90% identical), rat Abhd4 (87% identical), tropical clawed frog abhd4 (69% identical), zebrafish abhd4 (62% identical), Drosophila melanogaster puml (48% identical), Caenorhabditis elegans C31H5.1 (11% identical), and 6 more. Paralogues in human: ABHD5 (55% identical), EPHX4 (19% identical), EPHX2 (18% identical), ABHD8 (16% identical), MEST (16% identical), ABHD6 (15% identical), EPHX3 (15% identical), ABHD14A (12% identical), ABHD11 (12% identical), SERHL2 (11% identical), ABHD14B (11% identical), BPHL (10% identical).
Diseases named in the same sentence as ABHD4 in open-access papers:
ABHD4 is named in the same sentence as 19 diseases in open-access papers, as found by Europe PMC text mining. Sharing a sentence is not in itself a finding about the gene and the disease. The quoted sentences say what the papers report.
Obesity (2 papers, 2023 to 2025). Accumulation of substantial excess body fat. "The human cohort, an outbred rat model, and our diet-induced obese mouse study demonstrate for the first time that adipose ABHD4 gene expression is positively associated with obesity, suggesting a previously unappreciated role for ABHD4 in controlling adipose TAG homeostasis." (PMID 37352974, 2023). "However, it is unknown whether Abhd4 is a causal or a reactive gene to obesity." (PMID 37352974, 2023). "We further examined the relationship between adipose ABHD4 expression and obesity." (PMID 37352974, 2023). "During adipogenic stimulation, Abhd4 KO pre-adipocytes had increased adipogenesis and lipid accumulation, suggesting Abhd4 is responding to (a reactive gene), not contributing to (not a causal gene), adiposity, and may serve as a mechanism for protecting against obesity." (PMID 37352974, 2023).
bladder cancer (1 paper, 2020). "To better understand the role of ECs and NAEs in bladder cancer, we analyzed gene expression data from TGCA database regarding the metabolic pathway of the ECS, comprising the synthetic enzymes (PLCB1-4, PTPN22, ABHD4, GDE1, DAGLA, DAGLB, and NAPE-PLD) and the hydrolytic ones (FAAH, NAAA, and MGLL)." (PMID 32260109, 2020).
brain malformations (1 paper, 2020). "Thus, it is conceivable to postulate the pivotal neurological importance of ABHD4-dependent developmental anoikis which eradicates those pathologically detached cells that may represent a risk for future brain malformations, such as dysplasias, heterotopias, or even brain tumors." (PMID 32868797, 2020).
cataract (1 paper, 2020). Partial or complete opacity of the crystalline lens of one or both eyes that decreases visual acuity and eventually results in blindness. "This might indicate that a VPS13D or ABHD4 mutation causes retinal dystrophy and cataracts." (PMID 31876103, 2020).
colorectal cancer (1 paper, 2025). A primary or metastatic malignant neoplasm that affects the colon or rectum. "Among these, genes with positive coefficients (ABHD4, ABHD8, YJEFN3, CRYAB, and HSPA1A) were found to be risk factors, suggesting that their increased expression is associated with worse prognoses in colorectal cancer patients." (PMID 41293172, 2025). "In this study, we constructed a prognostic nomogram incorporating ABHD4, YJEFN3, and key clinical parameters to improve individualized survival prediction in colorectal cancer (CRC)." (PMID 41293172, 2025). "To further elucidate the functional relevance of ABHD4 and YJEFN3 as independent prognostic biomarkers, we explored their expression patterns in different cellular compartments of the colorectal cancer tumor microenvironment using the TISCH2 single-cell transcriptomic database." (PMID 41293172, 2025).
hepatoma (1 paper, 2020). "Because ABHD4 is unable to activate ATGL, we examined whether amino acid-swaps between the paralogs transfer the ability to activate ATGL for lipid droplet lipolysis and HCV assembly in our hepatoma cells." (PMID 32542055, 2020).
myocardial infarction (1 paper, 2021). Gross necrosis of the myocardium, as a result of interruption of the blood supply to the area, as in coronary thrombosis. "For acute STEMI patients, myocardial infarction was verified by persistent ST-segment changes and significant increase in cardiac troponin in all patients, similar to the marked differential expression of ABHD4 mRNA regulating RNA in the STEMI patients compared with healthy controls." (PMID 34208452, 2021).
myocardial ischemia (1 paper, 2021). A disorder of cardiac function caused by insufficient blood flow to the muscle tissue of the heart. "Results also go in hand with the ontology bioinformatics evidence that (FENDRR lncRNA, miRNA-197-5p, and miRNA-221-3p) networks synergistically regulate the ABHD4 mRNA expression in ACS, and thus shed light on a novel molecular mechanism in myocardial ischemia." (PMID 34208452, 2021).
ovarian carcinoma (1 paper, 2018). A malignant neoplasm originating from the surface ovarian epithelium. "ABHD4 is a novel regulator of anoikis sensitivity because ABHD4 knockdown could inhibit anoikis in prostate cells and reduce anoikis sensitivity in nasopharyngeal and ovarian cancer cells, while the overexpression of ABHD4 increased anoikis sensitivity." (PMID 29794032, 2018).
prostate carcinoma (1 paper, 2016). A carcinoma that arises from epithelial cells of the prostate gland. "Suppression of another alpha/beta hydrolase member, ABHD4, was found to increase resistance to anoikis in RWPE-1 prostate cancer cells." (PMID 27323405, 2016).
schizophrenia (1 paper, 2015). A major psychotic disorder characterized by abnormalities in the perception or expression of reality. "As outlined in S11 Table, seven of these genes have, to varying degrees, plausible links to cognition (i.e. DGKB, NPS, VPS13B, RBM20, ABHD4, ESRRB, and DOPEY2), with some active in systems implicated in schizophrenia pathology (NPS, DGKB, ABHD4, ESRRB)." (PMID 25860228, 2015).
unstable angina (1 paper, 2021). "Thus, it shed light on the underlying molecular mechanism associated with the ABHD4 mRNA panel and its regulatory RNA panel in unstable angina and STEMI patients." (PMID 34208452, 2021). "Additionally, the expression pattern for ABHD4 mRNA regulating RNA panel in unstable angina and acute STEMI were compared with healthy participants." (PMID 34208452, 2021). "Moreover, there was a concomitant upregulation in the expression of ABHD4 mRNA and miRNA-197-5p by 444-fold and 10-fold in unstable angina compared with healthy participants, and by 1.54-fold and 4.5-fold in STEMI compared with UA, respectively." (PMID 34208452, 2021).
tumor (3 papers, 2020 to 2025). "Interestingly, ABHD4 showed higher expression in stromal cell populations, including fibroblasts and endothelial cells, compared to both tumor and immune cells." (PMID 41293172, 2025). "Moreover, transwell and wound healing assays revealed that the knockdown of either gene significantly impaired the migratory and invasive capabilities of CRC cells, suggesting that both ABHD4 and YJEFN3 are positively associated with tumor cell aggressiveness." (PMID 41293172, 2025). "In addition, silencing ABHD4 and YJEFN3 suppressed CRC cell proliferation and motility, validating their role in tumor progression and suggesting their potential as therapeutic targets with clinical relevance." (PMID 41293172, 2025). "This suggests that ABHD4 may exert its tumor-promoting effects through modulating the stromal components of the TME, such as extracellular matrix remodeling or angiogenesis, rather than direct oncogenic activity in tumor cells." (PMID 41293172, 2025).
cancer (2 papers, 2020 to 2025). A tumor composed of atypical neoplastic, often pleomorphic cells that invade other tissues. "Given the importance of lipid reprogramming in cancer, ABHD4 may promote CRC progression through lipid signaling modulation." (PMID 41293172, 2025).
ABHD4 also shares sentences with these, for which no sentence is quoted: artery occlusion (1 paper); brain tumors (1); heterotopias (1); metastatic cancer (1); Retinal dystrophy (1).